CXCL10 (C-X-C motif chemokine ligand 10)
Diseases named in the same sentence as CXCL10 in open-access papers (continued):
Sharing a sentence is not in itself a finding about the gene and the disease.
breast carcinoma (continued). "CXCL10 acts on CD4 + and CD8 + T cells to enhance antitumor immunity, and the serum level of CXCL10 in breast cancer patients is positively correlated with tumor size and ER status." (PMID 36797662, 2023). "Studies have shown that induction of CXCL10 and CXCL11 expression in breast cancer cells enhances the infiltration of CD8 T cells." (PMID 37388244, 2023). "A broader analysis of CXCL10 and CCL17 in CD169+ TAMs originating from various breast cancer subtypes and stages will be needed to assess their relationship in more detail." (PMID 37404831, 2023). "Surprisingly, compared to ob-aT bASCs, ln-aT bASCs are less efficient in stimulating the proliferation of epithelial-like breast cancer cell lines BT474, MCF7 and MDA-MB-361, defying their secretion of cytokines such as FGF/FGF2, CSF3, CXCL10 and LIF." (PMID 36710348, 2023). "Chemical inhibition of cGAS or TBK1 led to significantly reduced production of the IRF3 target CXCL10 in 66cl4 cells, indicating that the cGAS-STING-TBK1 pathway is important for IFN-I expression in the metastatic mouse breast cancer cells." (PMID 36882786, 2023). "In both the mammary carcinoma and fibrosarcoma cells, secretion of CCL2, CCL3, CCL4, and Cxcl10 was upregulated after poly(I:C) transfection." (PMID 35737804, 2022). "CAIX promoted the production of known soluble mediators of breast cancer metastasis, CXCL10, CCL5, and G-CSF, by hypoxic breast cancer cells." (PMID 35719975, 2022). "A sequencing analysis for 1,310 breast cancer patients demonstrated the relevance of CXCL10 and HRD, identifying CXCL10 as biomarker for anti-PD-1/PD-L1 therapy." (PMID 36704336, 2022). "In both breast cancer cell lines, anti-IFNAR1 antibody completely blocked 4HC induction of Igtp, but only partially inhibited the induction of Oasl1 and Cxcl10." (PMID 36187936, 2022). "Similar with CXCL10, administration of sitagliptin resulted in higher concentrations of bioactive CCL11 in the TME of hepatocellular carcinoma and breast cancer, leading to increased migration of eosinophils into solid tumors." (PMID 33757558, 2021). "A more detailed analysis of 1100 patients with breast cancer (BRCA) revealed significant positive correlations between Il12b, Ifng, Ccl4, Ccl5, Cxcl9, and Cxcl10 gene expression levels and tumor infiltration of CD8+ T cells and M1 macrophages." (PMID 34446712, 2021). "In the lung metastasis of breast cancer, IL-1α and IL-1β secreted by breast cancer cells induce the production of CXCL9 and CXCL10 in lung fibroblasts through NF-κB signal transduction, thus promoting the growth of lung metastasis." (PMID 33722297, 2021). "CXCL10 induced cell proliferation, migration and epithelial-mesenchymal transition in MCF-7 and MDA-MB-231 breast cancer cell lines." (PMID 34504204, 2021). "Several differentially expressed mRNAs in HER2-positive breast cancer (including CXCL2, CXCL12, CXCL10, CXCL11, CXCL9 and CXCL14) were enriched in the biology processes of chemokine receptor binding and chemokine activity." (PMID 34257572, 2021). "We confirmed miR-200c-dependent upregulation of GM-CSF (CSF2), CXCL10, and CCL2 after transient transfection of miR-200c mimic compared to scramble (Scr) control in mouse mammary carcinoma and human TNBC cells." (PMID 34045467, 2021). "We found that the positive relationship between CXCL10 and the ICB-related genes was not only present in breast cancer, but also in 32 other cancer types." (PMID 34158843, 2021). "In breast cancer, CAFs secrete a variety of cytokines, including CXCL10, IL6, and IL8, which promote glycogenolysis and inhibit glycogen synthesis in breast cancer cells, ultimately leading to an increase in glycolysis." (PMID 34540683, 2021). "The chemokine CXCL10 and its receptor CXCR3 play a role in breast cancer metastasis and osteoclast activation." (PMID 32253815, 2020).
breast carcinoma (continued). "Specifically, IL-1α and IL-1β secreted by breast cancer cells induce CXCL9 and CXCL10 production in lung fibroblasts via NF-κB signaling, fueling the growth of lung metastases." (PMID 32198421, 2020). "Stimulation of MDA-LM2, SUM-LM1, and primary patient-derived breast cancer cells with recombinant CXCL9 and/or CXCL10 increased oncosphere formation, and this was reversed by addition of CXCR3i." (PMID 32198421, 2020). "To analyze the role of these chemokines in metastasis, we implanted MDA breast cancer cells co-expressing CXCL9 and CXCL10 bilaterally into the fourth mammary fat pads of female, nonobese, diabetic-severe combined immunodeficiency gamma (NSG) mice." (PMID 32198421, 2020). "The results indicated that the expression levels of CXCL9, CXCL10, CXCL11, and CXCL13 were marked higher in breast cancer tissues than in normal tissues, while the expression levels of CXCL1, CXCL2, CXCL3, and CXCL12 were lower inversely." (PMID 32963527, 2020). "Although there is no direct evidence supporting CXCL10 and CCL20-mediated TAM infiltration in prostate cancer, CXCL10 and CCL20 promote TAM recruitment in colorectal and breast cancer, respectively." (PMID 32971847, 2020). "For example, CCL2, CCL5, CXCL8, and CXCL12 can promote breast cancer, while CXCL9, CXCL10, and CCL16 can inhibit breast cancer." (PMID 32253815, 2020). "For example, CXCL10 affects the tumor microenvironment and plays important role in breast cancer progression, CXCL9 is identified as a biomarker in breast cancer." (PMID 31874629, 2019). "Of them, CXCL10, CXCL9, CCL11, CCR8, and GNG13 up-regulate breast cancer, while the other genes download-regulate breast cancer." (PMID 31874629, 2019). "CXC motif chemokine ligand 10 (CXCL10) and its receptor CXC motif chemokine receptor 3 (CXCR3), play important roles in the motility of breast cancer cells." (PMID 30177620, 2018). "In epithelial breast cancer cells, decreased mRNA levels for CXCR3B were induced by upregulation of CXCL10." (PMID 29416784, 2018). "A. canaliculatum ethanolic extract (ACE) inhibits TNFα-induced migration of MDA-MB-231 metastatic breast cancer cells and prevents TNFα-induced CXCR3 and CXCL10 expression through inhibition of the IκB kinase (IKK)-mediated NF-κB pathway." (PMID 30177620, 2018). "Our results show that ACE prevents TNFα-induced migration of MDA-MB-231 metastatic breast cancer cells and inhibits TNFα-induced CXCR3 and CXCL10 expression through inhibition of the IκB kinase (IKK)-mediated NF-κB pathway." (PMID 30177620, 2018). "Within the IFN genes, GBP1, CXCL10, IRF1, and STAT1 were described previously to be part of a tumor relapse-free signature in breast cancer patients." (PMID 30486871, 2018). "In contrast, CXCL10 and IGFBP-3 were shown to have anti-malignant properties by anti-angiogenic action or the inhibition of breast cancer cell proliferation." (PMID 28763032, 2017). "Overexpression of the IRX2 transcription factor in BT-549 and Hs578T breast cancer cells leads to concordant repression of CCL5, CXCL8 and CXCL10 mRNA expression." (PMID 26560478, 2015). "In breast cancer, NK cells take advantage of their own production of IFN-γ to enhance the secretion of chemokines CXCL9, CXCL10, and CXCL11 by tumor cells, which in turn accelerate the infiltration of CXCR3 expressing NK cells into the tumor site." (PMID 25110692, 2014). "We recently reported that in Th1 cytokine enriched microenvironment, MIG/CXCL9 and IP-10/CXCL10 were upregulated while IL-1β and IL-6 were downregulated with concomitant reduction in the percentage of MDSC in a 3D breast cancer model." (PMID 23394575, 2013). "Functional assays using microfluidic devices and degranulation tests revealed that lactate-exposed NK cells exhibited reduced chemotaxis and diminished cytotoxicity against MCF-7 and MDA-MB-231 breast cancer spheroids, accompanied by decreased CXCL9 and CXCL10 production." (PMID 41896548, 2026).
breast carcinoma (continued). "The interaction between CXCL6 secreted by breast cancer cells and CXCR6 on naïve MSCs leads to the induction of CXCL10 secretion by MSCs, which in turn acts on CCR3 on breast cancer cells, facilitating the recruitment of MSCs and promoting breast cancer metastasis." (PMID 40676710, 2025). "Transcriptomic studies have shown that PVT can increase the level of Il-24 mRNA and downregulate the level of Cxcl10 mRNA in MDA-MB-231 cells, whereas IL-24 can inhibit the growth of various tumor cells, including breast cancer cells, and induce the apoptosis of tumor cells." (PMID 40076586, 2025). "In addition, IL-24 can exert antitumor effects through CXCR4/CXCL12, and CXCL10, CXCL12 and CXCR4 are highly expressed in breast cancer tissues." (PMID 40076586, 2025). "Several studies have demonstrated that increased CXCL10 expression correlates with improved prognosis in various human cancers, including high‐grade serous ovarian carcinoma, colorectal cancer (CRC), hepatocellular carcinoma, and breast carcinoma." (PMID 39443817, 2024). "Intriguingly, the proportion of CXCL10+ cDCs in TNBC was much higher than that in estrogen receptor-positive (ER+) tumors, and the number of macrophages in TNBC was highest among the three breast cancer subtypes." (PMID 39104420, 2024). "IP-10/CXCL10 is a pro-tumorigenic chemokine and is secreted mainly by malignant rather than non-malignant tissues, correlated with the progression of breast cancer." (PMID 38541912, 2024). "In addition, breast cancers (BRCA) with high expression of CCL5 and TNFSF15 and ovarian cancers (OV) with high expression of CXCL10 exhibited better prognoses." (PMID 37980406, 2023). "Most studies on CXCL10 in breast cancer have focused on CXCL10 expression in the breast cancer cells, rather than the effect of macrophage derived CXCL10." (PMID 37404831, 2023). "Among these different CAF subtypes, iCAFs are reported to have a particular effect on chemoresistance in breast cancer patients, probably due to their high secretion of cytokines involved in therapy resistance, such as CXCL1–3, CCL2, CSF3, CXCL10, IL1β and LIF." (PMID 36710348, 2023). "Notably, the cytokines CCL5/RANTES, CXCL10/IP-10, and ICAM/CD54 increase tumour cell motility and invasion, with CXCL10/IP-10 and ICAM/CD54 also enhancing a metastatic phenotype in breast cancer tumour cells." (PMID 36949770, 2023). "IP-10 (CXCL10) has also been demonstrated to induce cell proliferation, migration, and epithelial to mesenchymal transition in MCF-7 and MDA-MB-231 breast cancer cell lines, which would contribute to a more aggressive profile supportive of greater tumor volume in BCW0 mice." (PMID 35681702, 2022). "In the next step, we employed a wound healing assay to evaluate whether CXCL10 promotes breast cancer cell migration in MCF-7 and MDA-MB-231 by observing cell migration after 24 h and 48 h of CXCL10 treatment." (PMID 34504204, 2021). "In this model, breast cancer cells secrete CXCL16 and MSC secrete CXCL10." (PMID 33800554, 2021). "CXCL10 is over-expressed in several kinds of cancers, and it is reported to regulate cancer progression, such as colorectal cancer (CRC), cervical cancer, ovarian cancer (OC), and breast cancer (BC)." (PMID 34544905, 2021). "Overexpression of CXCL10 is considered to be a favorable prognostic factor in TNBC, and high levels of TNFAIP3 expression are correlated with poor overall survival in HER2+ breast cancer and TNBC." (PMID 33102239, 2020). "In line with the observed high IL1A/B mRNA and secreted protein levels by metastatic breast cancer cells, treatment with CM from MDA-LM2 or SUM-LM1 cancer cells induced a stronger upregulation of CXCL10 in MRC-5 fibroblasts compared to CM from parental cell counterparts." (PMID 32198421, 2020). "Interestingly, CXCL10, CXCL11, and ISG20 are IFN-γ-regulated genes, which is consistent with the presence of interferon signature found in breast cancer from AA patients." (PMID 32714862, 2020).
breast carcinoma (continued). "A similar prediction could be made using five genes most differentially expressed in the breast cancer stroma, PSPHL, CXCL10, CXCL11, ISG20, and GMDS." (PMID 32714862, 2020). "CXCL10, also known as IFN-g-inducible Protein 10, plays an important role in promoting the homing of immune cells that mediates the subsequent death of cancer cells in breast cancer." (PMID 32963527, 2020). "Besides, HECTD3, PSMB10, UBD, UBE2C, and UBE2S involved in the ubiquitin proteasome pathway, as well as CCL2, CCR1, CXCL10, CXCL11, and IL2RG implicated in the cytokine–cytokine receptor interaction pathway, might be used for evaluating the efficacy of neoadjuvant chemotherapy in breast cancer." (PMID 29685151, 2018). "Indeed, a critical role for CXCL10 and to a lesser extent CXCL9 and CXCL11 was found in promoting breast cancer development." (PMID 29379506, 2017). "AMG487 inhibits CXCR3 signaling by obstructing binding of CXCR3 ligands and has been shown to inhibit in vitro CXCR3-mediated cell migration by the CXCR3 chemokines, CXCL9, CXCL10, and CXCL11, and to inhibit lung metastasis in a mouse model of metastatic breast cancer." (PMID 25798946, 2015). "CXCL10/IP-10 exhibits tumor-promoting ability: CXCR3 and its ligands CXCL10/IP-10 may be involved in tumor progression and metastasis in human breast cancer cell lines." (PMID 26379707, 2015). "Both CXCL10 and its receptor CXCR3 are on the other hand over-expressed in many tumours and have been connected to poor prognosis and metastasis in a number of cancers, including colon cancer, multiple myeloma, breast cancer and basal cell carcinoma." (PMID 24395654, 2014). "IFN-γ exposed breast cancer cells were used as controls in the subsequent experiments, because IFN-γ is a strong inducer of CXCR3 ligand expression, and the anti-tumor effects of CXCL9 and CXCL10 have been shown to be IFN-γ dependent in mouse models." (PMID 22333315, 2012). "CXCL9 and CXCL10 were not released into the culture medium of unstimulated MCF-7 or MDA-MB 231 breast cancer cells, whereas IFN-γ induced both cell types for CXCL9/10 secretion in a dose-dependent manner." (PMID 22333315, 2012). "Importantly, except for the clusters of CLEC9A+ cDC1s, CD1C+ cDC2s, and LAMP3+ cDCs,2 a discrete cluster of CXCL10+ cDCs, which was previously not reported in breast cancer, was identified based on top marker gene expression." (PMID 39104420, 2024). "A small retrospective study suggested that serum CXCL10 levels alone may serve as a prognostic factor in breast cancer, although no validation cohort was available, and multivariate analysis was not performed." (PMID 38594742, 2024). "However, poly(I:C) alone did not induce IFNβ, IL-8, Ccl5, or Cxcl10 mRNAs in a panel of six human breast carcinoma cell lines." (PMID 35737804, 2022). "Since high levels of CXCL10 were previously shown to activate the MAPK-ERK pathway in human glioma cells and breast cancer cells we examined whether downregulation of this chemokine, following miR-15a-5p overexpression, affects the MAPK-ERK cascade in myeloid and lymphoid cells." (PMID 34785791, 2022). "However, mammary carcinoma cells responded to poly(I:C) transfection with the upregulation of Cxcl10 and IL-6 but not TNFα mRNA levels." (PMID 35737804, 2022). "In addition, CAFs provide CXCL9 and CXCL10 to contribute to the CSC phenotype and proliferation of metastatic breast cancer cells, which bind to CXCR3 and activate JNK-IL-1 signaling in breast cancer cells; thus, a positive loop is established and MAFs are further activated." (PMID 34112258, 2021). "In a previous study which evaluated expression of CXCL10 in 6 cases of breast cancer (comprised of 3 cases of DCIS and 3 cases of invasive carcinoma) compared to normal breast using immunohistochemistry, invasive carcinoma showed markedly increased expression of CXCL10." (PMID 34504204, 2021).
breast carcinoma (continued). "Therefore, CCL2, CCR1, CXCL10, CXCL11, and IL2RG might be involved in neoadjuvant chemotherapy in breast cancer via the cytokine–cytokine receptor interaction pathway." (PMID 29685151, 2018). "To study the release of the two chemokines CXCL9 and CXCL10 from breast cancer cells we investigated regulation of protein secretion by supplying the inflammatory cytokines IFN-γ and TNF-α, which are both present in breast cancer tissues and known to induce CXCR3 ligands in other cell types." (PMID 22333315, 2012). "Moreover, targeting STAT3 in human breast cancer cells was reported to suppress the tumor progression by regulating the expression of crucial proteins in tumor milieu, such as survivin, chemokines (CCL5 and CXCL10) and proinflammatory cytokines (IL-6, IL-5, TNF-a, and IFN-γ)." (PMID 33957948, 2021). "As previous study has reported that blocking of STAT3 in breast cancer cells induced an antitumor immune response involving CD4+ T cells, which may ameliorate TME via secretion of cytokines, such as TNF-α, IFN-γ, IL-6, and IL-5, as well as chemokines CCL5 and CXCL10." (PMID 33957948, 2021). "Among the inversely correlated genes were four chemokines, CCL5, CXCL9, CXCL10 and CXCL11 indicating that IRX2 might be actively involved in the regulation of chemokine secretion by mediating the transcriptional repression of these chemokines in breast cancer cells." (PMID 26560478, 2015). "CXCL10 induced decreased epithelial marker (E-cadherin) expression after 24 h, but not after 48 h in MCF-7 breast cancer cell line." (PMID 34504204, 2021). "This is in agreement with clinical studies in human breast cancer identifying CXCL9, rather than CXCL10 or CXCL11, as a potential biomarker for diagnosis of breast cancer and therapy response, suggestive of its protective role in breast cancer biology." (PMID 22333315, 2012). "Interestingly, CXCL10, IRF1, and STAT1, shown to be expressed in breast cancers of patients who did not relapse, were also induced by EAD." (PMID 30486871, 2018).